PCDHB11 (protocadherin beta 11)
Description:
Potential calcium-dependent cell-adhesion protein. May be involved in the establishment and maintenance of specific neuronal connections in the brain.
Synonyms: PCDH-BETA11; ME2
Tractability: Antibody: its Gene Ontology location is reachable by antibodies, with high confidence; UniProt places it where antibodies can reach, with medium confidence; UniProt predicts a signal peptide or a membrane-spanning region; the Human Protein Atlas places it where antibodies can reach. PROTAC: ubiquitination databases record sites on it.
Gene: Protein-coding gene on chromosome 5 (141,199,610 to 141,203,779, forward strand). Ensembl gene ENSG00000197479.
Subcellular location: Cell membrane
Subcellular location (Human Protein Atlas): Plasma membrane
Gene Ontology:
Molecular function: cell adhesion molecule binding; calcium ion binding
Biological process: calcium-dependent cell-cell adhesion; cell adhesion; chemical synaptic transmission; nervous system development; synapse assembly; homophilic cell-cell adhesion
Cellular component: membrane; plasma membrane; synapse
Genetic constraint (gnomAD): Loss-of-function variants: 0 observed, 0.13 expected, observed/expected ratio (o/e) 0, 90% interval 0 to 1.89. That is too few expected variants to judge how well the gene tolerates losing a copy. Missense variants: 1,150 observed, 1,011.8 expected, observed/expected ratio (o/e) 1.14, 90% interval 1.08 to 1.19. Synonymous variants: 522 observed, 434.85 expected, observed/expected ratio (o/e) 1.2, 90% interval 1.12 to 1.29.
Homologues: Orthologues: chimpanzee PCDHB11 (97% identical), mouse Pcdhb19 (75% identical). Paralogues in human: PCDHB12 (89% identical), PCDHB14 (77% identical), PCDHB3 (75% identical), PCDHB2 (75% identical), PCDHB8 (75% identical), PCDHB13 (74% identical), PCDHB16 (74% identical), PCDHB10 (74% identical), PCDHB4 (74% identical), PCDHB5 (74% identical), PCDHB9 (73% identical), PCDHB15 (73% identical), and 49 more.
Diseases named in the same sentence as PCDHB11 in open-access papers:
PCDHB11 is named in the same sentence as 4 diseases in open-access papers, as found by Europe PMC text mining. Sharing a sentence is not in itself a finding about the gene and the disease. The quoted sentences say what the papers report.
diabetes (1 paper, 2022). "There were 8 differentially methylated genes (CDH2/PCDHB10/PCDHB11/PCDHB14/PCDHB16/PCDHB3/PCDHB6/PCDHB9) in the LAA subgroup and 1 (CDH2) in the SVD subgroup after adjusting for smoking, drinking, history of hypertension and diabetes, and blood lipid levels (p < 0.05)." (PMID 35480311, 2022).
melanoma (1 paper, 2016). A malignant, usually aggressive tumor composed of atypical, neoplastic melanocytes. "With regard to the physiological importance of β-protocadherins, the only data in humans so far have revealed a very high expression of PCDHB11 and PCDHB13 on the melanoma cell surface." (PMID 27068704, 2016).
tumor (2 papers, 2015 to 2021). "Here, subtype‐specific events involving either DNA copy number loss or CpG promoter methylation were found to involve TENC1, RARA, PCDHB11, PCDHB14, PCDHGA2 and PCDHGB2 indicative of candidate tumor suppressor genes in this context." (PMID 25468711, 2015).
PCDHB11 also shares sentences with these, for which no sentence is quoted: Hypertension (1 paper).